MYO15A (myosin XVA)
Description:
Myosins are actin-based motor molecules with ATPase activity. Unconventional myosins serve in intracellular movements. Their highly divergent tails are presumed to bind to membranous compartments, which would be moved relative to actin filaments. Required for the arrangement of stereocilia in mature hair bundles (By similarity).
Synonyms: MYO15; DFNB3
Tractability: PROTAC: ubiquitination databases record sites on it.
Gene: Protein-coding gene on chromosome 17 (18,108,756 to 18,179,802, forward strand). Ensembl gene ENSG00000091536.
Subcellular location: Cell projection, stereocilium; Cytoplasm, cytoskeleton
Pathways (Reactome):
Sensory Perception: Sensory processing of sound by inner hair cells of the cochlea; Sensory processing of sound by outer hair cells of the cochlea
Gene Ontology:
Molecular function: actin filament binding; ATP binding; cytoskeletal motor activity
Biological process: endocytosis; sensory perception of sound; response to light stimulus
Cellular component: extracellular exosome; actin cytoskeleton; actin-based cell projection; cytoskeleton; myosin complex; stereocilium; stereocilium bundle
Genetic constraint (gnomAD): Loss-of-function variants: 307 observed, 379.57 expected, observed/expected ratio (o/e) 0.81, 90% interval 0.74 to 0.89. The upper end of that interval is the gene's LOEUF score, 0.89, which puts it in group 3 of 6, group 1 being the genes least tolerant of losing a copy. Missense variants: 4,563 observed, 4,618.3 expected, observed/expected ratio (o/e) 0.99, 90% interval 0.96 to 1.01. Synonymous variants: 1,944 observed, 1,920.6 expected, observed/expected ratio (o/e) 1.01, 90% interval 0.97 to 1.05.
Gene-disease validity (ClinGen):
ClinGen rates the evidence that MYO15A causes each of these diseases.
nonsyndromic genetic hearing loss (autosomal recessive): Definitive. A disease characterized by hearing loss that is not part of a larger syndrome.
Homologues: Orthologues: chimpanzee MYO15A (98% identical), macaque MYO15A (96% identical), mouse Myo15a (83% identical), rat Myo15a (82% identical), guinea pig MYO15A (79% identical), zebrafish myo15aa (46% identical), tropical clawed frog MYO15A (43% identical), zebrafish myo15ab (37% identical), Drosophila melanogaster Myo10A (25% identical). Paralogues in human: MYO7A (17% identical), MYO7B (17% identical), MYO10 (16% identical), MYH7 (12% identical), MYH6 (12% identical), MYH1 (12% identical), MYH2 (12% identical), MYH4 (12% identical), MYH3 (12% identical), MYH8 (12% identical), MYH7B (12% identical), MYH10 (12% identical), and 32 more.
Diseases named in the same sentence as MYO15A in open-access papers:
MYO15A is named in the same sentence as 29 diseases in open-access papers, as found by Europe PMC text mining. Sharing a sentence is not in itself a finding about the gene and the disease. The quoted sentences say what the papers report.
deafness (69 papers, 2011 to 2025). An inherited or acquired condition characterized by the complete loss of the ability to hear from one or both ears. "We conclude that MYO15A’s nucleation activity is the key polymerization effect disrupted by the jordan deafness mutation in vitro." (PMID 39843411, 2025). "Our data further show that the jordan deafness mutation profoundly inhibits the ability of MYO15A to stimulate actin polymerization, linking this activity to hearing loss." (PMID 39843411, 2025). "Our data show that MYO15A-induced actin nucleation is a key process targeted by the jordan deafness mutation, and argue that this activity is critical for stereocilia elongation and hearing." (PMID 39843411, 2025). "Mutations in human and mouse Myo15A cause DFNB3-associated deafness and vestibular dysfunction, with defects in stereocilia growth and actin bundle regulation." (PMID 40627464, 2025). "Failure of complementation in Myo15ajd/sh2 mice confirms that the p.D1647G mutation in Myo15a is the cause of recessive deafness in the jordan pedigree." (PMID 39843411, 2025). "We conclude that the wild-type MYO15A motor domain stimulated actin polymerization, whilst the deafness-causing jordan mutant not only blocked this stimulatory activity, it reduced the overall extent of actin polymerization." (PMID 39843411, 2025). "All reported mutant Myo15a mouse alleles cause profound deafness (MGI:1261811), measured from P14 onwards." (PMID 39843411, 2025). "Meanwhile, the influence of various genes like MYO15A associated with deafness on the outcomes of Cochlear implantation has been identified." (PMID 38167320, 2024). "In a genome-wide disequilibrium study conducted in 1995, an association between MYO15A and deafness was first discovered in an isolated village in Indonesia, where approximately 2% of the population was affected by hearing loss." (PMID 38167320, 2024). "Further investigations using myosin XVa-deficient mice have confirmed the role of MYO15A variants in the development of deafness." (PMID 38167320, 2024). "Validation of single nucleotide variants and confirmation of the diagnosis in a family with MYO15A-associated deafness." (PMID 36743950, 2023). "We have previously reported on one ARNSHL family including two affected siblings and identified MYO15A c.5964+3G > A and c.8375 T > C (p.Val2792Ala) as the possible deafness-causing variants." (PMID 36401330, 2022). "In light of our findings and review of the literatures, 58 splice-site variants in MYO15A are correlated with a severe deafness phenotype, composed of 46 canonical splice-site variants and 12 non-canonical splice-site variants." (PMID 36401330, 2022). "It is reported that MYO15A mutations cause sensorineural HL in human autosomal recessive deafness 3 (DFNB3, OMIM #600316)." (PMID 35346193, 2022). "Whirlin colocalizes and interacts with two other causal proteins for deafness, MYO15A (DFNB3) and EPS8 (DFNB102), forming a tripartite complex that controls actin polymerization and elongation of the actin core at the tips of the stereocilia." (PMID 35444606, 2022). "Whereas in the cohort of Korean ARNSHL patients, MYO15A mutations were recognized as the fourth most important deafness gene variants after those detected in other genes like GJB2, SLC26A4 and CDH23." (PMID 35346193, 2022). "Here we add to the pathogenic allelic heterogeneity of MYO15A by implicating two new pathogenic variants in MYO15A, one splice-altering and one frameshift, that co-segregate with deafness in Ashkenazi Jewish families." (PMID 34733312, 2021). "Our kinetic study represents an important step toward understanding how pathogenic mutations in MYO15A cause human deafness DFNB3." (PMID 33372036, 2021). "Currently, pathogenic variants in six myosin genes (MYO3A, MYO6, MYO7A, MYH14, MYH9, and MYO15A) have been linked to human deafness." (PMID 34733312, 2021).
deafness (continued). "Our finding further extends the MYO15A gene mutation spectrum and enriches our knowledge of genotype-phenotype correlation in MYO15A-related deafness." (PMID 34093702, 2021). "WES of the family trio revealed the presence in the proband of three missense variants in the MYO15A gene (NM_016239.3), which is known to be associated with sensorineural non-syndromic autosomal recessive deafness (DNF3B, MIM#: 600613)." (PMID 35052694, 2021). "MYO15A was the causal gene of autosomal recessive deafness (type 3), and 112 pathogenic variants in this gene have been identified in ClinVar." (PMID 32682410, 2020). "Here, we report a nonconsanguineous Chinese Han family with profound ARNSHL, in which compound heterozygous mutations in MYO15A were identified as the probable cause of the deafness." (PMID 32617096, 2020). "The p.E1221Wfs∗23 and c.6177+1G>T compound heterozygous mutations in MYO15A are the probable cause of congenital, profound deafness in the Chinese Han family." (PMID 32617096, 2020). "Mutations in MYO15A are frequently detected in patients with severe to profound SNHL, and MYO15A is considered to be one of the most common deafness‐causing genes responsible for NSHL in Chinese patients." (PMID 33095980, 2020). "The large size of the gene and the heterogeneity of the mutations have precluded the inclusion of MYO15A screening into routine deafness genetic examinations using conventional sequencing strategies." (PMID 31581539, 2019). "As a result, MYO15A variants are responsible for non-syndromic autosomal recessive deafness (DFNB3, OMIM 600316) in humans, whereas variants of homologous Myo15 genes lead to deafness and vestibular dysfunction in mice (shaker-2)." (PMID 30953472, 2019). "Fifteen Chinese autosomal recessive non-syndromic hearing loss (ARNSHL) individuals with MYO15A variants (8 males and 7 females) from 14 unrelated families, identified by targeted gene capture of 127 known candidate deafness genes, were recruited." (PMID 30953472, 2019). "By performing a genome-wide disequilibrium study in 1995, MYO15A was found to be associated with deafness for the first time in Indonesian residents." (PMID 30068307, 2018). "Sanger sequencing confirmed that these two MYO15A gene variants co-segregated with deafness in this family." (PMID 30068307, 2018). "Exactly as literatures state, MYO15A variants have usually been regarded as the cause of congenital severe to profound deafness." (PMID 29849560, 2018). "In our previous study, MYO15A pathogenic variant was reported at a frequency of 2.1% in nonsyndromic autosomal recessive deafness, which was the fourth most common deafness gene in Korea, following SLC26A4, GJB2 and CDH23." (PMID 29482514, 2018). "Herein, we also demonstrate that some MYO15A mutant alleles can cause postlingual onset of progressive partial deafness." (PMID 29482514, 2018). "We identified compound heterozygous mutations in MYO15A including a novel nonsense mutation, which induced pathogenic effects on the protein function and therefore should be responsible for the deafness in this family." (PMID 30068307, 2018). "The analysis of NGS data led to the identification of five novel variants in the known deafness genes MYO15A, LOXHD1, TBC1D24, and OTOG, all of which were associated with pathogenicity, and categorized according to the ACMG guidelines." (PMID 30139988, 2018). "Thereafter, the frequency of MYO15A pathogenic variant was reported in up to 9.9% of deafness cases in Turkey." (PMID 29482514, 2018). "In mice, a variation in the motor domain of Myosin 15a causes the deaf-circling shaker 2 (sh2) phenotype and in humans, variations in Myo15a are the cause for DFNB3 type deafness." (PMID 28821934, 2017). "Mutations in the human ortholog MYO15A similarly cause non-syndromic autosomal recessive deafness, DFNB3." (PMID 26302205, 2015).
deafness (continued). "Most of the previously reported mutations of MYO15A causing congenital severe to profound deafness were found in the motor head and the tail domains." (PMID 24949729, 2014). "More than 50% of the families carry mutations in GJB2 while mutations in MYO15A account for about 5% of recessive deafness." (PMID 24949729, 2014). "Mutations in MYO15A have also been identified in families originating from Pakistan, India and Japan, and were associated with profound deafness in the patients." (PMID 24926664, 2014). "Bi-allelic mutations in 15 less commonly screened deafness genes were identified in 28 deaf probands, with mutations in MYO15A, GPR98, TMC1, USH2A and PCDH15 being relatively more frequent (≥3 probands each)." (PMID 23767834, 2013). "Moreover, a deafness-causing mutation in the MYO15A actin-binding interface inhibits nucleation activity but still preserves some movement on filaments in vitro and partial trafficking on stereocilia in vivo." (PMID 39843411, 2025). "The findings from studies conducted on myosin XVa-deficient mice have demonstrated that variants in the MYO15A gene can lead to deafness through two distinct mechanisms: the failure to develop mechanosensory hair bundles and the inability to sustain mature stereocilia." (PMID 38167320, 2024). "Based on these results, we believe that MYO15A variants may be the cause leading to the postlingual onset of partial deafness, the molecular mechanism of which requires further investigation." (PMID 35346193, 2022). "Therefore, the MYO15A gene was rarely sequenced in familial segregated deafness unless significant genetic linkage data implicated the presence of the DFNB3 locus." (PMID 35346193, 2022). "In the present study, we have also identified the missense/non-sense heterozygous variants in the OTOG p.(Val1813Gly), SLC26A4 p.(Tyr556∗) CDH23 p.(Ala1631Val), GJB2 p.(Arg165Trp), and MYO15A p.(Arg1965His) genes which are predominant to cause deafness among Indian populations." (PMID 34113375, 2021). "By targeted next-generation sequencing of 140 deafness-causative genes in the proband, compound heterozygous mutations c.3658_3662del and c.6177+1>T in MYO15A (NM_016239) were identified as the only candidate pathogenic mutations consistent with a presumably autosomal recessive inheritance." (PMID 32617096, 2020). "Our study expanded the mutation spectrums of TMC1 and MYO15A and illustrated that genotype-phenotype correlation in combination with next-generation sequencing may improve the accuracy for genetic diagnosis of deafness." (PMID 32802042, 2020). "Most recessive mutations in MYO15A are associated with congenital, severe-to-profound deafness, except for mutations affecting the N-terminal domain of MYOXVA which may result in milder hearing loss with residual hearing of low frequency." (PMID 32617096, 2020). "Some recessive MYO15A variants can cause postlingual onset of progressive partial deafness." (PMID 29482514, 2018). "We also found two families carrying MYO15A pathogenic variants, which were expected to cause congenital severe-to-profound hearing loss, but resulted in postlingual onset of progressive partial deafness with residual hearing at low frequencies." (PMID 29482514, 2018). "Based on these results, we suggest that MYO15A may be a causative gene responsible for the postlingual onset of progressive partial deafness, which in turn requires the expansion of the phenotypic spectrum of MYO15A pathogenic variants." (PMID 29482514, 2018). "Three mutations, c.3971C>A (p.A1324D), c.4011insA (p.Q1337Qfs∗22), and c.9690+1G>A, were detected in MYO15A gene (NM_016239), which were cosegregated with the disease, suggesting that these mutations may be the etiology of deafness in this ARNSHL family." (PMID 29849560, 2018). "The homozygous c.9316dupC variant in the MYO15A gene co-segregated with the phenotype of deafness in the ARNSHL family and might be the disease-causing mutation." (PMID 26308726, 2015).
deafness (continued). "In the Pakistani population mutations in MYO15A account for 5% of the recessive deafness." (PMID 24949729, 2014). "Mutations in MYO15A are responsible for the DFNB3 form of deafness." (PMID 24926664, 2014). "These mutations may result in pathogenesis and deafness and may have important roles in the functions of myosin XVA." (PMID 23865914, 2013). "Twelve homozygous mutations in known deafness genes, of which eight are novel, were identified in 12 families: MYO15A-p.Q1425X, -p.S1481P, -p.A1551D; LOXHD1-p.R1494X, -p.E955X; GIPC3-p.H170N; ILDR1-p.Q274X; MYO7A-p.G2163S; TECTA-p.Y1737C; TMC1-p.S530X; TMPRSS3-p.F13Lfs*10; TRIOBP-p.R785Sfs*50." (PMID 23226338, 2012). "Interestingly, his brother (II.1), besides being homozygous for the AGBL5 variant, also harbored a homozygous, likely pathogenic, nonsense variant (NM_016239.4:c.7121C>G, p.(Ser2374Ter)) in MYO15A, a gene associated with profound, congenital, nonsyndromic deafness (OMIM * 602666)." (PMID 39672920, 2025). "Expanding screening via next-generation sequencing (NGS) to include other established (e.g., MYO15A, OTOF, CDH23, TMC1) and emerging deafness genes would significantly enhance diagnostic yield and capture a broader spectrum of genetic causes." (PMID 41181184, 2025). "In Taiwan, common deafness-associated genes include GJB2, SLC26A4, OTOF, MYO15A, and MTRNR1, which were similar to those found in other populations." (PMID 40943139, 2025). "In Taiwan, the common deafness-associated genes assessed, in order of prevalence included GJB2, SLC26A4, OTOF, MYO15A, and MT-RNR1." (PMID 38840095, 2024). "MYO15A and OTOF were among the first genes identified to be associated with deafness using conventional approaches." (PMID 37189200, 2023). "Further efforts are needed to analyze other frequent deafness-predisposing genes, such as TMC1, USH2A, CDH23 and MYO15A in an expanded panel in future studies." (PMID 36389375, 2022). "Genetic causes, particularly pathogenic variants in several highly prevalent deafness genes (e.g., SLC26A4, GJB2, MYO15A and OTOF) are associated with favorable CI outcomes, whereas certain imaging findings such as CND are associated with unfavorable outcomes." (PMID 36009393, 2022). "We observed that the MYO15A variants, located in its N-terminal, motor and FERM domains, led to partial deafness with better residual hearing at low frequencies." (PMID 35346193, 2022). "Using targeted next-generation sequencing of 414 known deafness genes, we identified compound heterozygous mutations in TMC1 and MYO15A as the genetic causes of the hearing loss in those families." (PMID 32802042, 2020). "Recent comprehensive next‐generation sequencing (NGS) analysis has helped clarify genetic epidemiology; i.e., GJB2 is the predominant deafness‐causing gene, with the other common genes being CDH23, SLC26A4, MYO15A, COL11A2, and MYO7A." (PMID 32027099, 2020). "In this study, by targeted next-generation sequencing of 414 known deafness genes, we identified compound heterozygous mutations p.R34X/p.M413T in TMC1 and p.S3417del/p.R1407T in MYO15A in two recessive Chinese Han deaf families." (PMID 32802042, 2020). "Common deafness-associated genes in Taiwanese families, in order of prevalence, included GJB2, SLC26A4, OTOF, MYO15A, and MTRNR1, which are similar to those found in other populations." (PMID 31581539, 2019). "All seven of these families have variants in seven different known deafness genes, LRTOMT, LHFPL5, TMPRSS3, OTOF, MYO15A, ESRRB, and KCNE1." (PMID 31835641, 2019). "Common deafness-associated genes in the Taiwanese patients assessed, in the order of prevalence, included GJB2, SLC26A4, OTOF, MYO15A, and MTRNR1, which were similar to those found in other populations." (PMID 31581539, 2019). "The variant in the MYO15A is now a globally noted cause of ARNSHL and this deafness locus has been designated DFNB3 (OMIM, #600316)." (PMID 31250571, 2019).